CCL2 (C-C motif chemokine ligand 2)
Diseases named in the same sentence as CCL2 in open-access papers (continued):
Sharing a sentence is not in itself a finding about the gene and the disease.
cancer (continued). "Our study showed that doxycycline suppressed both LPA- and TNFα-induced nuclear translocation of NF-κB and blocked the LPA-induced secretion of IL-6, CCL2 and CXCL2 in cancer cells." (PMID 28178994, 2017). "Increased CCL2 expression was present in PDAC tissues and a portion of human PDAC cancer cell lines." (PMID 29379802, 2017). "In line with their high potential for functional impact, CXCL1, CXCL5, CCL2, and IL-8 were also significantly induced by TRAIL in different cancer cell lines, as determined by ELISA, antibody-based cytokine array, and qPCR." (PMID 28212753, 2017). "For example, cancer cells stimulate expression of adipokines and adipocytokines (including IL-6, IL-1β, CCL2, CCL5, TNF-α, MCP-1, leptin), proteases, and inhibitors (e.g., MMP-11, PAI-1)." (PMID 28101337, 2017). "Our results demonstrated that in the presence of ionizing radiation either RKO or SW1463 cancer cells increased mRNA expression levels of the macrophage pro-inflammatory markers TNF, IL6, CCL2 and CCR7 as well as of the anti-inflammatory marker CCL18." (PMID 27513864, 2016). "The cancer pathway finder PCR array revealed 9 genes, including ACSL4, BIRC3,CA9, CCL2, FLT1, FOXC2, G6PD, IGFBP3 and SNAI2, with significantly altered expression in the siRNA-treated MCF-7 cells." (PMID 27478411, 2016). "Plenty of researches suggest that CCL2/CCR2 is related to poor outcome and metastatic events in several cancers." (PMID 26701209, 2016). "CCL2/CCR2 signaling was demonstrated to play crucial roles in the metastatic process, stimulating cancer cell proliferation, invasion and migration, and promoting metastatic outgrowth and colonization." (PMID 26885690, 2016). "The experiments revealed that the mediators of each aspect of cancer cell behavior are diversified: proliferation was driven by IL-6, migration by CXCL8 and CCL2, invasion by IL-6, MMP-3 and uPA, and EMT by TGF-β1." (PMID 26284488, 2015). "We also previously reported that NF-κBp65 gene expression is increased in the subcutaneous white adipose tissue of cachectic cancer patients, concomitantly to up-regulation of its inflammatory target genes IL-1β, TNF-α, CCL2/MCP-1, and IκB-α." (PMID 26732354, 2015). "MCP-1/CCL2 expression was increased 4-fold in the co-cultures above monocytes and more than 40-fold above cancer cells cultured alone." (PMID 26317041, 2015). "The chemokine MCP-1/CCL2 is produced by a variety of tumors and plays an important role in cancer progression." (PMID 26167165, 2015). "Recent studies have provided direct evidence that MSCs are recruited in TME by a broad range of soluble factors which are secreted by cancer cells and CSCs, including IL-6, VEGF and bFGF, CCL2, SDF-1α, and HMGB1." (PMID 25136593, 2014). "Monocyte chemoattractant protein-1 (MCP-1)/CCL2 is a chemokine regulating the recruitment of monocytes into sites of inflammation and cancer." (PMID 24432017, 2014). "The analysis also confirmed down-regulation of CCL2, IL18, and up-regulation of Wnt7b genes in macrophages grown under co-culture conditions with cancer cells." (PMID 22353646, 2012). "The real-time qPCR confirmed the CCL2, CCL3, CD163, CSF1R, MMP9, HIF1, VEGF-C up-regulation in cancer cells grown as a co-culture with macrophages." (PMID 22353646, 2012). "We found up-regulation of the highly potent macrophage attracting factors: CCL2 (MCP-1), CCL3 (MIP-1α), CCL4 (MIP-1β) and CCL5 (RANTES) as well as CCR5 in cancer cells grown as co-culture with macrophages." (PMID 22353646, 2012). "For the sake of simplicity, in the following sections of the manuscript the four chemokines (CCL2, CCL5, CXCL8, CXCL10) will be referred together as “cancer-related chemokine cluster”." (PMID 24213226, 2012). "Finally, the promising therapeutic potential of targeting specific chemokine signaling axes, such as CCL2/CCR2 and CXCL10/CXCR3, was discussed as a strategy to improve the efficacy of cancer immunotherapy." (PMID 41635851, 2026).
cancer (continued). "By mRNA profiling, we found that these cytokines, including CCL2, GM-CSF, and CXCL8, might be important downstream targets of N4BP1 in establishing the cancer microenvironment." (PMID 41513619, 2026). "Additionally, the interactions between chemokines, including CXCL1, CXCL8, and CCL2, and ACKR1, expressed by endothelial cells, were notably greater in MHC-II+ cancer cells than in MHC-II− cancer cells." (PMID 41281745, 2025). "CCL2 and CXCL8, secreted by CAFs, induce cancer cell proliferation and invasion." (PMID 40136652, 2025). "Moreover, senescent cancer cells are capable of recruiting and inducing M2 polarization by secreting monocyte chemoattractant protein-1 (MCP-1/CCL2), thereby suppressing their innate immune response to cancer cells." (PMID 40765820, 2025). "Overall, the mechanisms that regulate CCL2 and HGF appear distinct and multi-factorial and could depend on the cancer type." (PMID 40736024, 2025). "Additionally, IFN‐inducible chemokines CCL2, CCL5, and CXCL10 were found to be upregulated at both mRNA and protein levels in multiple cancer cells post‐irradiation." (PMID 40470716, 2025). "NF-κBp65 and its target CCL2 were found to be higher in adipose tissue of cancer cachectic patients compared to non-cachectic cancer or cancer-free patients." (PMID 40076892, 2025). "Moreover, TAM recruitment was found to be influenced by immune-related genes such as CCL2, CCR2, CXCR4, and CCR5, which suppress immune responses and facilitate cancer progression." (PMID 39968182, 2025). "In addition to CXCL12, there are other chemokines that hold promise for regulating the migration of cancer cells, such as CXCL8, CXCL16, CCL2, and CXCL10." (PMID 39715221, 2024). "Increased CCL2 expression in activated fibroblasts required STAT3 activation by diverse BC-secreted cytokines, and in turn, induced NOTCH1 expression and the CSC features in BC cells, constituting a cancer–stroma–cancer signaling circuit." (PMID 39335478, 2024). "CCL2 has also been shown to positively impact tumorigenesis in PDAC, through its ability to attract TAMs, improve cancer cell self-renewal capabilities, and enhance cancer cell survival in response to radiotherapy." (PMID 38339310, 2024). "In addition, CAAs also secrete chemokines and other inflammatory cytokines, such as C-C motif chemokine ligand 2 (CCL2) and IL-1β, to stimulate adipocytes and promote cancer progression." (PMID 39040042, 2024). "CCL2 is a prognostic factor in HCC and suppression of CCL2/CCR2 axis can suppress TAMs toward M2 polarization and impair the progression of murine liver tumor model through induction of T cell-mediated anti-cancer immune reactions." (PMID 38997297, 2024). "Several studies have evidently shown that chemokines (such as CCL2, CCL5, CXCL1, and CX3CL1) are involved in neuronal sensitization or microglia activation in the spinal cord, and some of these chemokines contribute to the development of cancer pain." (PMID 39641645, 2024). "CCL2 produced by omental adipocytes binds to CCR2, activating the PI3K/Akt/mTOR pathway and its downstream effectors HIF-1α and VEGF-A, promoting migration and omental metastasis in cancer cells." (PMID 39408927, 2024). "The main chemokine that affects the recruitment of monocyte/macrophages during the inflammatory process and cancer progression is C-C motif chemokine ligand 2 (CCL2), also known as monocyte chemoattractant protein 1 (MCP1) produced by injured and infected tissues, as well as by TCs." (PMID 38542388, 2024). "Upregulated DEGs included chemokines and receptors (CCL2, CCL3L1, CCL4L2, and CX3CR1), known for their roles in recruiting myeloid-derived suppressor cells (MDSC) and prompting metastasis in certain cancer types." (PMID 38903524, 2024).
cancer (continued). "Cancer cells release growth factors, such as FGF-2, VEGF, PDGF, EGF, TGFβ, and cytokines and chemokines, the core group consisting of CCL2, CCL5, IL-6, IL-8, as well as other soluble factors that activate fibroblasts and modulate CAF gene expression patterns and their metabolism." (PMID 37046676, 2023). "In this study, we do not see the enhancement of CCL2 production by macrophages co-cultured with cancer cell spheroids, probably because the macrophage cultivation medium supplemented with L929-CM already contained a significant amount of CCL2 (2.6 ng/mL)." (PMID 37445941, 2023). "It has been observed in a multitude of cancers that CCL2 is expressed in higher amounts by CSCs than non-CSC counterparts." (PMID 38035101, 2023). "Notably, VEGF-A, TNF-α, CCL2, IL-6, and IFN-γ were significantly elevated in the Cancer TIF1-γ-DM group than in the Non-cancer TIF1-γ-DM group." (PMID 36357631, 2023). "Interestingly, the findings suggested a correlation between HIF1AN in breast malignancy and PDCD1, LAG3, CTLA4, and GZMB of T cell exhaustion as well as chemokine ligand CCL2 of TAMs." (PMID 36816977, 2023). "In addition, we sorted out murine neurons out of DRG of TPAC mice and other cell types (cancer cells, myeloid cells, and lymphoid cells) from the primary tumors of TPAC mice and KPC and cross compared the expression levels of CCL2." (PMID 37607005, 2023). "In addition to CCL17 and CCL22, CCL2 (monocyte-chemo-attractant protein 1, MCP-1) critically drives TAM formation, and its receptor CCR2 is involved in cancer progression." (PMID 37371612, 2023). "The current study identified VEGF-A, TNF-α, CCL2, IL-6, and IFN-γ (CCL2, IL-6, and IFN-γ after Bonferroni correction) as additional plasma biomarkers reflecting cancer presence, in addition to anti-TIF1-γ antibody, among anti-TIF1-γ antibody-positive DM patients." (PMID 36357631, 2023). "Moreover, TAM recruitment depends on immune-related genes such as CCL2, CCR2, CXCR4, and CCR5, which can promote cancer development by promoting immunosuppression." (PMID 37275880, 2023). "The interaction between CCL2 and CCR2 is essential for macrophage-related functions in cancer progression, such as mediating cancer-related inflammation, regulating the balance between M1 and M2 macrophages, facilitating the recruitment of TAMs, and providing anti-apoptotic signals." (PMID 37628994, 2023). "Therefore, we focused on upregulated secretome genes that included several known cachexia mediators described in pan-cancer and NSCLC, such as IL6, IFNG, LIF, CCL2, and CSF3." (PMID 36774484, 2023). "It is worth noting that growth factors (FGF, PDGF) and hypoxia may activate fibroblasts to CAFs, which produce pro-cancer cytokines such as CXCL-1, -2, -3, -12, and -14; CCL-2, -5, and -17; and IL-18." (PMID 37736898, 2023). "This suggests that the CCL2/CCR4 signaling pathway affects not only the chemoattraction and the migration machinery of cancer cells, but additionally modulates the neural ingrowth and innervation of cancer." (PMID 37607005, 2023). "While the cancer presence alone did not elicit gene expression changes in these adipose tissues, there was a significant increase in Ccl4 (in pmWAT only), Ccl2 and Il6 in both WATs in the HFD/MOSETICv group." (PMID 38264656, 2023). "In monocytes and macrophages, cancer EVs can activate Toll-like receptor-mediated signaling cascade, triggering NFκB- and STAT3-mediated production of proinflammatory cytokines – IL-6, IL-8, IL-1β, CCL2, G-CSF, and TNF-α." (PMID 37397375, 2023). "TAM-derived CCL2 and VEGF stimulate angiogenesis, allowing cancer cells to enter the circulation." (PMID 37208442, 2023). "Notably, chemokine (C-C motif) ligand 2 (CCL2) plays a critical role in macrophage recruitment and is involved in cancer cell proliferation, cancer metastasis, and the establishment of an immunosuppressive TME." (PMID 37915048, 2023).
cancer (continued). "Consequently, it seems that inhibition of the CCR2_CCL2 signaling pathway can downregulate EMT and reduces cancer progression through the inhibition of transcription factors such as Vimentin." (PMID 37325423, 2023). "The binding of CCL2 and its receptor CCR2 plays a central role in macrophage-related functions by mediating cancer-related inflammation, regulating the proportion of M1 and M2 macrophages, promoting the recruitment of TAMs and providing anti-apoptotic or angiogenic signals." (PMID 36173487, 2023). "Thus, CCL2 emerged here as a secreted molecule, which was induced by TGF-α, and potentially involved in the interactions between neurons and cancer cells." (PMID 37607005, 2023). "Patients with PC have been shown to have significantly higher CCL2 levels than patients without cancer." (PMID 36289628, 2022). "Moreover, the immunogenic dying cancer cells were proposed to trigger a pathogen response-like chemokine signature, the CXCL1, CCL2 and CXCL10 co-release." (PMID 36429101, 2022). "However, immunosuppressive chemokines such as CXCL8, CXCL5, CXCL12, CCL2, and CCL22 were generally upregulated across the 13 cancer types." (PMID 34841742, 2022). "Elevated levels of pADPr have also been associated with the release of various chemokines, including monocyte chemoattractant protein-1 (MCP-1 or CCL2), eotaxin (CCL11), macrophage inflammatory proteins MIP-1α (CCL3) and MIP-1β (CCL4), all of which are known to promote cancer invasion." (PMID 35585513, 2022). "Another work confirmed that a higher expression of CCL2 can be found in cancer tissue, and it is connected with a negative prognosis in CRC patients." (PMID 35407400, 2022). "In addition, the CCL2/CCR2 axis can promote cell survival by inhibiting autophagic death and apoptosis of cancer cells by activating the phosphatidylinositol 3-kinase (PI3K)/AKT/mammalian target of rapamycin (mTOR)-dependent pathway." (PMID 35281057, 2022). "Collectively, these data show how hypoxic cancer-derived EVs, via transfer of MIR-301, MIR-451, and CCL2, may be able to interfere with dendritic cells’ functioning, resulting in reduced antitumor immune reactions." (PMID 36010994, 2022). "Notably, this group of 9 genes also included CCL2, suggesting that stroma-secreted CCL2 is the important stromal factor in the TME in cancer patients." (PMID 34874922, 2022). "We also described the molecular mechanism of AAM polarization and therapeutic strategies for cancer-promoting AAM macrophages, including CCL2 monoclonal antibodies or CSF1R inhibitors, AAM re-acclimation targeting immune checkpoints, and new strategies to improve the “phagocytic ability” of cells." (PMID 36439090, 2022). "Moreover, CCL2 and its CCR2 receptor have been revealed to play pivotal roles in cancer metastasis’s early and late stages." (PMID 35955463, 2022). "Interestingly, TAMs (CCL2, CD86, and IL10), M1 [INOS(NOS2), IRF5, and COX2(PTGS2)] were significantly correlated with SHC1 expression in the three cancers." (PMID 35601500, 2022). "IL‐34 expression was detected in cancer cell lines but not in HMDMs, whereas M‐CSF and CCL2 expression was seen in HMDMs but not or rarely in cancer cell lines." (PMID 35132816, 2022). "Targeting CCR4 was also effective in disrupting CCL2-induced growth and metastasis without promoting cancer relapse." (PMID 36555280, 2022). "Moreover, the secretion of CCL2 in cancer milieu is regulated by activating transcription factor 4 (ATF4), which is produced in response to stress conditions in the cancer environment." (PMID 35408440, 2022). "Furthermore, we identified that CCL2 and CCR4 was highly expressed in cancer cells of HNSCC, indicating that CCL2 secreted by cancer cells possibly stimulates itself by autocrine or paracrine function." (PMID 35177591, 2022). "Cancer cells (i.e., CNA+) from the prepuberty disease state had significant high expression of genes involved in the innate immunity and chemokine signaling pathway (Ccl2, Ltf, Ccl7, Ccl20)." (PMID 35851387, 2022).
cancer (continued). "High levels of CCL2 in the serum and the TME have often been associated with poor prognosis no matter the type of cancer." (PMID 35664746, 2022). "Additionally, cancer cells promote monocyte recruitment through the release of chemotactic signals such as VEGFA, CCL2, CXCL12, semaphorin 3A (SEMA3A)." (PMID 34680425, 2021). "Furthermore, in the vast majority of solid cancer models, M2-like Mφs and/or TAMs at the cancer site differentiate in situ from circulating CCR2+CD14++CD16– classical monocytes, recruited via cancer cell-secreted CCL2." (PMID 34249942, 2021). "The secretion of pro-stemness paracrine factors such as insulin-like growth factors, inflammatory cytokines (IL-6 and IL-8), and chemokines (CCL2 and CCL5) promotes the conversion of cancer cells into cancer stem cells and reinforce the stemness of existing cancer stem cells." (PMID 34094963, 2021). "Thus, several investigations point at a few signaling molecules/signaling pathways involved in the NSCLC stromal cancer cell crosstalk, including IL6, TGFβ, and CCL2." (PMID 34950592, 2021). "Additionally, the contact bone marrow MSC-leukemic cell-VLA-4 and VCAM-I mediated increases factors contributing to cancer cell survival like IL-8, IL-6, VCAM-1, and CCL2, known to correlate with high infiltration of macrophages promoting cancer cell growth." (PMID 34680425, 2021). "In addition to recruiting myeloid cells, tumor cell-derived CCL2 activates C-C motif receptor (CCR) 2 on ECs, inducing vascular permeability and subsequent cancer cell extravasation." (PMID 36046433, 2021). "Furthermore, they can dampen antitumor immunity and promote cancer immune evasion via secreting immunosuppressive cytokines including TGF-β1, and recruiting MDSCs through CCL2 released in the TME." (PMID 33946048, 2021). "As illustrated above, the signaling axis of CCL2/CCR2 in monocytes/macrophages and T cells has a great impact on cancer immunity, and accumulating evidence also supports the concept that cancerous cells can directly employ CCR2 to promote survival/growth and metastasis." (PMID 34804061, 2021). "Due to the recruitment of monocytes, CCL2, CCL7, CCL8, and CCL13 are important in the pathogenesis of many diseases where an important role is played by monocytes and macrophages, in particular atherosclerosis, inflammatory bowel disease, and cancer." (PMID 33182504, 2020). "The expression of CCL2, CCL7, and CCL8 in CAF is very important in cancer." (PMID 33182504, 2020). "Thus, MYC and TWIST1 predict poor survival, CCL2/IL13 expression and M2-like TAM infiltration in human cancers." (PMID 31933479, 2020). "In addition, both GI and GII modulated the expression of Chemokine (C-C motif) ligand 2 (CCL2) and PDZ-LIM domain protein 4 (PDLIM4) genes which code for important regulators of cell migration and invasion in cancer tissues." (PMID 32085612, 2020). "Given the critical roles of CCL2 and CXCL5 in recruiting TAMs to neoplastic tissue, thereby contributing to cancer metastasis 30, 31, we investigated whether S100A14 plays a key role in orchestrating the recruitment of macrophages through CCL2 and CXCL5." (PMID 32483412, 2020). "We have demonstrated that Oligo-Fucoidan reduces IL-6 and MCP-1/CCL2 expression and secretion in the ETO-treated cancer cells; thus, Oligo-Fucoidan may control autocrine loops in cancer cells and paracrine pathways in the innate and/or adaptive immune systems." (PMID 32059469, 2020). "Both cancer and stroma cells contribute in MDSC accumulation in a CCL2-dependent manner." (PMID 32133298, 2020). "CAFs also contribute to M2 polarization by secreting multiple cytokines and stimuli including macrophage-colony stimulating factor, reactive oxygen species, IL-6, IL-8, CCL2, and CXCL6 as seen in multiple cancer model systems (e.g., PDAC, colorectal and esophageal squamous cell carcinoma)." (PMID 32957515, 2020).